MMP9 (matrix metallopeptidase 9)
Diseases named in the same sentence as MMP9 in open-access papers (continued):
Sharing a sentence is not in itself a finding about the gene and the disease.
tumor (continued). "In addition to that, ECM‐related gene such as MMP9 and MUC5B were prominently upregulated in poorly group, indicating that the expression of these genes in macrophages plays a pivotal role in influencing tumour differentiation." (PMID 40847563, 2025). "For instance, ROS increases the expression of MMP‐2 and MMP‐9 in fibrosarcoma cells, promoting the ECM breakdown, angiogenesis, release of growth factors such as cytokines, and inhibition of T‐cell proliferation and function that allow tumor cells to metastasize at distant locations." (PMID 40377005, 2025). "For example, the absence of MMP-9 expression in stroma-related cells in MMP-9−/− mice on a C57BL/6 background decelerate the synthesis of supportive tumor stroma and relevant immunosuppression, indirectly revealing the stroma-targeted mechanism of amino-biphosphonate treatment." (PMID 39861125, 2025). "CRISPR-Cas9 is a recent and revolutionary technique, as it is possible to perform gene editing specifically in the region of interest, which in this study was MMP-9, and evaluate the evolution of the tumor for a longer period, without stimulating all the adjacent effects of current treatments." (PMID 41273852, 2025). "Furthermore, the ECM breakdown and matrix remodeling might increase tumor invasiveness due to the expression of MMPs, such as MMP-1, MMP-2, MMP-3, MMP-9, and MMP-13 by human MSCs." (PMID 40784879, 2025). "Additionally, HIF-1α induces the expression of target genes, such as VEGF, GLUT-1, Matrix Metalloproteinase 9 (MMP-9), Stromal Cell-Derived Factor 1 alpha (SDF-1α), and BNIP3, further driving tumor angiogenesis, metabolic reprogramming, and anti-apoptotic processes." (PMID 40443737, 2025). "During EMT in tumor cells, the expression of proteins that promote cell-cell adhesion, such as E-cadherin, is decreased, while the expression of mesenchymal markers, including vimentin, MMP-2, and MMP-9, is increased, thereby enhancing cell migration and invasion capabilities." (PMID 41194934, 2025). "Further Western blot analysis showed that RRM2 regulated the expression levels of MMP2, MMP9 and EMT-related proteins (N-Cadherin, Vimentin, Snail), suggesting that RRM2 may promote tumor cell invasion and metastasis by promoting matrix degradation and inducing epithelial mesenchymal transition." (PMID 41333212, 2025). "Moreover, TLR9-mediated tumor progression involves the implication of various chemokines, particularly CCL2 and CCL5, along with matrix metalloproteinases (MMP), such as MMP-2 and MMP-9." (PMID 41157253, 2025). "Additionally, it inhibits matrix metalloproteinases Matrix Metalloproteinase-2 (MMP-2) and Matrix Metalloproteinase-9 (MMP-9), reducing invasiveness, and decreases reactive oxygen species (ROS) production, thereby limiting oxidative stress–induced tumor progression." (PMID 40978472, 2025). "However, in our study, homozygous deletion of Zeb1 in macrophages neither weakened the pro-malignant effect of TAMs on tumor cells, nor did it reduce Mmp9 expression." (PMID 40595293, 2025). "Previous studies have shown that this alkaloid can (i) inhibit tumor cell proliferation while at the same time inducing apoptosis; (ii) affect signaling pathways (e.g., MAPK/ERK and PI3K/Akt); and (iii) inhibit tumor cell migration and invasion (e.g., MMP-2 and MMP-9)." (PMID 40710294, 2025). "The study found that the MMP9 positive rate in TNBC tissues was 63.2%, compared to 32.5% in benign breast lesion tissues, suggesting that MMP9 plays a significant role in the development of TNBC and its high expression correlates with the tumor’s invasiveness and metastatic capabilities." (PMID 40356970, 2025). "Altered molecular targets, such as E-cadherin (CDH1), MMP9, Survivin (BIRC5), Cytokeratin 5 (KRT5), VEGFA, IL15, TNF-α (TNF), TRAIL (TNFSF10), and Tenascin-C (TNC), exhibited increased expression in our study, which correlates with their upregulation in tumor samples from individuals with OC." (PMID 40072102, 2025).
tumor (continued). "Our data revealed increased levels of MMP-9 on infected cancer cells, but also decreased levels of E-cadherin after the infection, which is described as a key event of EMT, permitting the separation of individual cells from the primary tumor mass, and therefore promoting cancer invasion." (PMID 39743544, 2025). "However, exposure to paclitaxel increased tumor growth and volume, which were reversed by ibuprofen that significantly modulated cytokine levels, suppressing MCP-1 and increasing TNF-α, IL-2, VEGF, and MMP-9." (PMID 40924302, 2025). "Cathepsin S or MMP9 inhibitors can be employed to reinforce the BBB, and when combined with anti-VEGF therapy, may suppress pro-angiogenic activity, thereby blocking early steps of tumor cell invasion and colonization." (PMID 41219968, 2025). "In a cohort of HCC patients, whether presenting lung metastasis or not, SRC‐1 expression and MMP‐9 expression were found to be higher in tumours with lung metastasis compared to primary HCC tumours." (PMID 38506084, 2024). "In addition, sympathetic nervous system activation can indirectly lead to the release of several protumour factors, including matrix metalloproteinase-9 (MMP-9), VEGF, TGF-β, IL-6 and IL-8, triggering a series of inflammatory responses to stimulate tumour recurrence and metastasis." (PMID 38912060, 2024). "Moreover, active STAT3 can promote tumor metastasis in a variety of human cancers via the upregulation of VEGF and other angiogenic factors such as angiopoietin, chemokines mediating tumor invasion, and matrix metallopeptidase-9." (PMID 38256080, 2024). "We found through gelatine zymography assays that CM derived from the co-culture experiments (MLKL-overexpressing tumour cells and macrophages) had an improved ability to digest gelatine, but this property was reversed by MMP inhibitors, MET inhibitors and GW, primarily affecting by MMP2 and MMP9." (PMID 39025845, 2024). "MMP-9 secreted from TANs may interact with insulin receptor substrate 1 (IRS-1), and further regulate the PI3K/AKT signaling pathway to contribute to the proliferation of tumor cells." (PMID 39582869, 2024). "Additionally, in gastric cancer the suppressive effects of kisspeptin on tumor invasion are believed to be mediated through downregulation of matrix metalloproteinases (MMPs), particularly MMP-9 and MMP-2, which are critical in tumor invasion and metastasis formation." (PMID 39199311, 2024). "In fact, MDSCs lacking MMP-9 are incapable of inducing tumor angiogenesis." (PMID 39691707, 2024). "Meanwhile, the increase in MMP-2 MMP-9, SNAI1 and TWIST1 protein levels in the IL-22 group suggests that IL-22 may regulate MMP expression by activating the PI3K/AKT signaling pathway, enhancing tumor cell invasion and metastasis." (PMID 39073546, 2024). "It has been demonstrated that activation of PI3K/AKT by matrix metalloprotease 9 (MMP9) can induce the PI3K/AKT downstream transcription factor Snail to facilitate EMT via vimentin upregulation and E-cadherin downregulation, resulting in enhanced tumour invasion and metastasis." (PMID 38303024, 2024). "Additionally, our immunofluorescence assay of subcutaneous tumor tissues indicated that ZSTK474 effectively suppressed the expressions of vascular endothelial growth factor VEGF and matrix metalloproteinases MMP2 and MMP9." (PMID 39466763, 2024). "Taken together, our results underscore the potential of MMP9 as a clinical marker independent of tumor size that may help lay the foundation for preoperative classification of adherent VS." (PMID 38887507, 2024). "This presents a challenge for using MMP9 as a consistent predictive marker, as its expression might not consistently reflect tumor behavior across various treatment regimens." (PMID 39664453, 2024). "Interestingly, the administration of PEM caused a marked downmodulation in the expression of N‐cadherin and MMP‐9, whereas E‐cadherin was upregulated, indicating that PEM could reduce tumor metastasis to the liver." (PMID 37439412, 2023).
tumor (continued). "In addition, MMP-2, MMP-9, and MMP-14 cleave the TGF-β-binding protein 1 (LTBP-1) present in the ECM, leading to the release of ECM bound TGF-β, which helps establish a tumor-supportive environment." (PMID 37266453, 2023). "In addition, inflammatory cells within the tumor microenvironment may contribute to the production of tumor-promoting molecules, such as growth factors, pro-angiogenic cytokines, and enzymes that can promote invasion (e.g., CSF-1, EGF, VEGF, and MMP-9)." (PMID 36672343, 2023). "Tumor-derived suppressive factors binding to corresponding receptors leads to continuous activation of STAT3, which then upregulates expression of STAT3-related genes and produces proteins (survivin and cyclin) and matrix metalloproteinase-9 (MMP-9) that promote MDSCs expansion." (PMID 37006306, 2023). "AC-MCs could produce VEGF, PDGF, MMP9, and PGE2 to promote angiogenesis and tumor migration." (PMID 36644231, 2023). "Moreover, we found that the C4 subpopulation highly expressed cystatin B (CSTB), matrix metalloproteinase 9 (MMP9), chemokine C-C ligand 5 (CCL5), and macrophage migration inhibitory factor (MIF), which have the characteristics of promoting tumor cell migration and invasion." (PMID 37715019, 2023). "Furthermore, tumor hypoxia stimulates HIF-1 expression, increasing MMP-9 activity." (PMID 36837487, 2023). "Aberrant expression of VM production-related proteins (MMP2, MMP9, VEGFA, Laminin, Wnt3a, RHOA) as well as immune checkpoint (PD-L1) in tumors and the occurrence of EMT process are considered to be important drivers of VM formation and tumor development as well as metastasis." (PMID 37407689, 2023). "Furthermore, TAMs promote tumor cell invasion by mediating the degradation of the extracellular matrix through the involvement of cathepsins and matrix metalloproteinases (MMPs) such as MMP7, MMP2, and MMP9." (PMID 38258072, 2023). "The upregulated proteins, including MMP9 (matrix metalloproteinase-9), ADAMTS13 (ADAM metallopeptidase with thrombospondin type 1 motif 13) and CRP (C-Reactive Protein), are known to be involved in extracellular matrix remodeling, vascular permeability and tumor-promoting inflammation." (PMID 36831450, 2023). "It has also been shown to inhibit tumor cell proliferation, invasion, and metastasis by modulating the Ras/Raf/MEK and PI3K/Akt signaling pathways, which mediate a reduction in the expression of MMP2, MMP9, N-cadherin, Bcl-2, caspase, and other related proteins." (PMID 38067451, 2023). "More importantly, orlistat effectively attenuated tumor weight by inhibiting FAS and inducing apoptosis in all three diet intervention mouse groups (HFD, LFD, HFD-LFD), and decreased angiogenesis by reducing the expression of MMP-9 and VEGF of EC tumors in HFD and HFD-LFD mice." (PMID 37601677, 2023). "The expressions of various factors, including vascular endothelial growth factor (VEGF) and matrix metallopeptidase 9 (MMP-9), are upregulated in the ischemic and hypoxic environments, following TACE, which could be one of the mechanisms inducing tumor recurrence and metastasis." (PMID 37254146, 2023). "On the other hand, HMGB1 produced by the tumor-specific macrophages can regulate the microenvironment through IL-6/STAT3/(programmed death-ligand 1) PD-L1 pathway and IL-6/NF-κB/(matrix metalloproteinase 9) MMP-9 pathway leading to further immunosuppression and aggressive phenotypes of OSCC cells." (PMID 37511951, 2023). "Interestingly, we demonstrated that DHEA educated TAMs in a less aggressive phenotype, reducing the gene expression of several markers of TAM phenotype, including IL-6, MMP-9, VEGF, IL-10, and MPC-1, which sustain tumor invasiveness, angiogenesis, and metastasis." (PMID 36765778, 2023). "Therefore, we investigated whether LCN2, LOXL2, and MMP9 are interrelated in ECM remodelling, and whether LCN2/LOXL2/MMP9 form a complex to play a synergistic role in tumour progression." (PMID 37753805, 2023).
tumor (continued). "During tumor development, MMP2 and MMP9 may be involved in the regulation of tumor angiogenesis by undermining immunity, activating the TGF-β signaling, and releasing VEGF and bFGF, thus promoting the rapid growth and distant metastasis of tumor cells." (PMID 37144126, 2023). "MMP9 belongs to the matrix metalloproteinase family, which can degrade various protein components in the extracellular matrix (ECM) and disrupt the histological barrier that prevents tumor cell invasion, and therefore plays a key role in tumor invasion and metastasis." (PMID 38201487, 2023). "Stroma contains abundant inflammatory cells expressing MMP9 such as macrophages, specifically TAMs, or neutrophils, but we speculate that not all of them participate in the tumor microenvironment." (PMID 37296952, 2023). "In addition, matrix metalloprotenase-9 (MMP-9) produced by neutrophils can promote the release of vascular endothelial growth factor (VEGF) to promote angiogenesis and participate in the process of tumor growth and metastasis." (PMID 37152022, 2023). "A previous report indicated that SS could repress MMP-9 expression in tumor cells without affecting MMP-2 expression." (PMID 38098039, 2023). "Interestingly, in the absence of MMP9, vascular leakage increased due to enlarged endothelial gap junctions and decreased pericyte coverage, resulting in a better tumor response to doxorubicin treatment." (PMID 37908739, 2023). "In addition, experimental data showed that luteolin dramatically suppressed tumor growth of A375 cells in a mouse xenograft model, demonstrating that the anticancer activity is derived from the down-regulation of MMP-2 and MMP-9 expression via the PI3K/Akt pathway." (PMID 37110140, 2023). "The interaction of the formulation with MMP-9 in the tumor microenvironment triggered the release of the encapsulated gemcitabine and exhibited improved anticancer activity compared to the PEGylated nanovesicles without MMP-9 substrate." (PMID 37242560, 2023). "We also examined the regulation of MMP-9 expression in HNSCC cells, as we were interested in whether regulation occurs purely in BMSCs, or whether some form of regulation also occurs on the part of tumor cells." (PMID 36674806, 2023). "STAT3 had been found to be over-activated and played a tumor-promoting role in a variety of human cancers because STAT3 could act as a transcription factor to promote the expression of cyclin-B1, cyclin-D1, MMP2, MMP9 and other pro-tumor proteins." (PMID 37161425, 2023). "The results demonstrated that MCMD NPs could enhance drugs accumulation in tumors, and release DOX upon enzymatic degradation of matrix metalloproteinase-9 (MMP-9) peptide in the tumor microenvironment (TME), which enhanced the direct-killing effect of DOX on tumor cells." (PMID 37237292, 2023). "On the other hand, the bioactivity of lovastatin was recently found to reduce the expression of matrix metalloproteinase (MMP)-9 and MMP-2, as well as the suppression of the Ras isoprenylation, which could subsequently decrease the invasive ability of tumor cells." (PMID 36558925, 2022). "Neutrophils could enhance tumor angiogenesis via the production of VEGF and MMP9." (PMID 36555469, 2022). "On the other hand, MMP-9/MMP-2 protein expression may be downregulated by inhibiting the activation of Smad2/3 (pSmad2/3), thereby inhibiting the occurrence of EMT and weakening the metastatic ability of tumor cells." (PMID 35936728, 2022). "Interestingly, the expression levels of MMP9 were upregulated in 28 tumor types and downregulated only in LAML and THYM, whereas no statistical difference was achieved in DLBC, MESO, and UVM." (PMID 36211450, 2022).
tumor (continued). "In vitro and in vivo models support the conclusion that LPAL2 modulates tumor growth, metastasis and stemness phenotypes of HCC cell lines, and microarray profiling analysis and validation results suggest that LPAL2 regulates metalloproteinase-9 (MMP9) at the transcriptional level." (PMID 36010685, 2022). "Therefore, CAFs may contribute to HCC tumor progression by producing growth factors (EGF, FGF, HGF, and TGF-β), chemokines (SDF-1), cytokines (IL-6), and metalloproteinases (MMP-3 and MMP-9)." (PMID 35158892, 2022). "In contrast to C4-Mye enriched in blood, C6-Mye preferred tumor and paratumor tissue and highly expressed 591 genes, including the M2 macrophage marker gene MCR1 (CD206), and highly expressed the M2 macrophage-related protumorigenic genes TGF-β, IL10, VEGFA and MMP9." (PMID 35562760, 2022). "In addition, tumor tissue showed an increase in heparanase, MMP9, PPARγ, and IFNγ, while non-tumor adjacent tissue showed an increase in E-cadherin and COX2 and a decrease in IL-4R." (PMID 36139645, 2022). "Therefore, this study is the first to target MRTK, a rare tumour, in combination with the MMP inhibitor doxycycline, aiming to determine whether EMT, as well as the differential expression of MMP2 and MMP9, exists in MRTK." (PMID 36408277, 2022). "The balance between MMP-9 and TIMP-1 is thought to play a critical role in controlling extracellular-matrix turnover and the inhibition of tumor invasion and metastasis, therefore the decreased expression of TIMP-1 reported in our study may influence the tumor development and progression." (PMID 36518899, 2022). "Immunohistochemistry and western blotting analyses showed reduced protein expression of CHI3L1, PCNA, cyclin D1, Cdk 6, and MMP‐9, but the expression of cleaved caspase‐3 was increased; however, IL‐13Rα1 and IL‐13Rα2 levels were not changed in K284‐treated lung metastasis tumor tissues." (PMID 34758182, 2022). "Therefore, it can be speculated that FN1 and CLDN7 proteins may mediate tumor progression through the network interaction with LCN2 and MMP9." (PMID 36211450, 2022). "Neutrophils can also release matrix metalloproteinase-9 (MMP9), vascular endothelial growth factor (VEGF), and inflammatory mediators, such as interleukin 6(IL-6) and tumor necrosis factor-β (TNF-β), which promote the invasion, proliferation and distant metastasis of tumor cells." (PMID 35570842, 2022). "In addition to the increased expression of the prospective prostate CS/IC marker CD133, tumor hybrids also exhibited a decreased E-cadherin expression, but increased protein levels of AKT, MMP9, and vimentin, suggesting that hybrids may have undergone EMT." (PMID 35562905, 2022). "Moreover, in a murine model of HCC, intra-tumoral macrophages expressing MMP-9 were involved in ECM remodeling, thus favoring tumor progression, while, in another study, the presence of TAMs correlated with tumor vascularity, pointing towards the ability of TAMs to promote angiogenesis." (PMID 35158892, 2022). "Interestingly, our study showed that plasma MMP9 was not prognostic of tumor progression but was specifically predictive of bevacizumab response." (PMID 34980260, 2022). "Weak MMP9 expression was observed in 40% of the tumours, whilst 60% stained negative." (PMID 35756604, 2022). "MMP9 was found to be able to proteolyze extracellular signal proteins, mostly members of the CXC (C-X-C motif) chemokine family, regulating immune cell trafficking and, therefore, is considered as an important creator and coordinator of the tumor immune microenvironment (TIME)." (PMID 35406619, 2022). "However, the effect of some MMPs, like MMP-9, on CAC is bidirectional, which means they are involved in the pathogenesis of IBD and promote the metastasis and spread of malignant tumors, but also play a role in tumor suppression as well." (PMID 36776395, 2022).